BRCA1 (BRCA1 DNA repair associated)
Diseases named in the same sentence as BRCA1 in open-access papers (continued):
Sharing a sentence is not in itself a finding about the gene and the disease.
breast cancer (continued). "In another family (F2), BRCA1 Ex20dup was identified in a female who developed breast cancer (invasive ductal carcinoma, estrogen receptor positive (100%), HER2 normal expression) at 46 years (F2 IV:2)." (PMID 38195559, 2024). "The most prevalent germline mutations linked to breast cancer occur in the BRCA1 and BRCA2 genes (breast cancer gene 1 and gene 2), vital for DNA repair, carrying an average cumulative lifetime risk of approximately 70%." (PMID 39065193, 2024). "A recent investigation in a breast cancer cell line demonstrated a point mutation (E168Q) in the OLA1 gene, which impaired its ability to bind BRCA1." (PMID 38889130, 2024). "Although Poly (ADP-ribose) polymerase (PARP) inhibitors (PARPi) have been approved in multiple diseases, including BRCA1/2 mutant breast cancer, responses are usually transient requiring the deployment of combination therapies for optimal efficacy." (PMID 38802355, 2024). "Understanding BZA’s modulation of BRCA1 and ERα, along with their mechanistic interactions, is vital for comprehending its impact on breast cancer tumor suppressors and hormone receptors." (PMID 38398090, 2024). "BRCA1-2 represented 53.7%, and homologous recombination DNA damage repair (HR-DDR) genes associated with breast cancer risk accounted for 15.9%." (PMID 38893140, 2024). "It has been shown that VEGF and HIF are more highly expressed in BRCA1/2 PVs than sporadic breast cancers, and this has been attributed to the fact that BRCA1 can bind to the VEGF gene promoter, inhibiting its transcription and thus reducing VEGF secretion." (PMID 39682099, 2024). "In particular, BRCA1 PVs have been found to have unique effects on the tumour microenvironment (TME) compared to other sporadic breast cancers." (PMID 39682099, 2024). "This study established a Markov model to analyze the cost-effectiveness score of Talazoparib in treating BRCA1/2 mutant breast cancer in China and the US." (PMID 38886516, 2024). "This study sought to assess the patterns and outcome of CNS metastases in breast cancer patients with PVs in BRCA1/2 in comparison to BRCA wild-type (BRCA-WT) patients." (PMID 38365640, 2024). "The prevalence of pathogenic variants in the specific genes BRCA1 and BRCA2 in unselected breast cancer patients has been estimated to be 2–2.5%, similarly to what has been reported in the Southern Swedish population." (PMID 38491334, 2024). "We found both mRNA expression and protein expression of SOSTDC1 in BRCA1‐wildtype breast cancer cells were lower than that in BRCA1‐mutant ones, which was also confirmed by public dataset analysis." (PMID 38864559, 2024). "The observed associations in this study were in line with previously reported effect sizes for lifestyle factors and breast cancer in the general population and BRCA1/2 patients." (PMID 38473316, 2024). "Here we investigate PARP inhibition combined with clinical photon or proton beams in the context of BRCA1 wild-type and mutant breast cancer models." (PMID 39730675, 2024). "Suppression of HR gene function can occur via other mechanisms such as promoter methylation of HR genes, such as BRCA1 in breast cancer, or regulatory proteins such as RBBP821–23." (PMID 38589664, 2024). "BRCA1 PVs have also been thought to induce aberrant interaction of breast cancer cells with other cell surface and cytoskeletal proteins responsible for the regulation of EMT such as P-cadherin, beta-catenin, vimentin, and cytokeratins." (PMID 39682099, 2024). "Approximately 70% of breast tumors containing germline BRCA1 mutations are diagnosed as triple-negative breast cancer (TNBC), a highly aggressive subtype of breast cancer associated with poor outcomes due to limited treatment options." (PMID 38869771, 2024). "Our findings here show for the first time that in K14-Cre conditional murine model, combined deletion of Wwox and Brca1 synergizes to accelerate mammary tumor formation in vivo." (PMID 38499540, 2024).
breast cancer (continued). "We previously reported that GATA3 functions downstream of BRCA1 to suppress aberrant differentiation in breast cancer." (PMID 38627785, 2024). "Depletion of Gata3, like that of Brca1, promoted DNA damage accumulation in breast cancer cells in vitro and in basal-like breast cancers in vivo." (PMID 38627785, 2024). "Since the identification of the BRCA1 and BRCA2 genes, germline pathogenic and likely pathogenic variants, herein collectively termed PVs, have been associated with increased risks of breast cancer in both men and women." (PMID 38609177, 2024). "In this study, we discovered that depletion of Gata3, like that of Brca1, impairs DNA damage repair in breast cancer cells in vitro and in vivo." (PMID 38627785, 2024). "To further investigate if SYCP2 can function independently of BRCA1, we tested HCC1937 and HCC1954, two breast cancer cell lines defective for BRCA1." (PMID 38383600, 2024). "Three compounds, N-acetyl-N-acetoxy chlorobenzenesulfonamide (NANAC), A-443654, and CHIR-124, were validated to reduce BRCA1 protein levels and sensitize breast cancer cells to the toxic effects of olaparib." (PMID 38993666, 2024). "The same numbers of BRCA1 and BRCA2 mutations and the same ratios of luminal and triple negative (TN) breast cancer cases were observed." (PMID 39544591, 2024). "Recent research has shown that estrogen can suppress the expression of the BRCA1 gene by stimulating the release of nitric oxide in ER+ breast cancer cells." (PMID 39156700, 2024). "A study combining data from 22 investigations found that by age 70, 65% of women with BRCA1 and 45% with BRCA2 variants develop breast cancer." (PMID 39598249, 2024). "On the other hand, some of the remaining potential miR-660-5p targets interact with the Akt and BRCA1 pathways, which are involved in key processes in breast cancer progression, such as proliferation, migration, and invasion." (PMID 39709500, 2024). "Research indicates that the median age of breast cancer onset is 42 years for BRCA1 carriers and 48 years for BRCA2 carriers." (PMID 39421188, 2024). "It is a fact that BRCA1-related tumors are TN more frequently, and previous data show similarities between those and sporadic basal-like breast carcinomas, with regard to morphological and immunohistochemical features." (PMID 39596307, 2024). "Pathogenic variants (PVs) in BRCA1, BRCA2, PALB2, RAD51C, RAD51D, and BRIP1 cancer susceptibility genes (CSGs) confer an increased ovarian cancer (OC) risk, with BRCA1, BRCA2, PALB2, RAD51C, and RAD51D PVs also conferring an elevated breast cancer (BC) risk." (PMID 38334999, 2024). "To perform this TWAS, we utilized summary statistics for ER + BC from the Breast Cancer Association Consortium (BCAC) and for ER- BC from a meta-analysis of BCAC and the Consortium of Investigators of Modifiers of BRCA1 and BRCA2 (CIMBA)." (PMID 38515142, 2024). "BRCA1 and BRCA2 are the most common mutated genes seen in patients with ovarian and breast carcinomas." (PMID 38344545, 2024). "Mutations in the BRCA1 and/or BRCA2 genes (BRCAm) increase the risk of developing breast cancer (BC) and are found in ~5% of unselected patients with the disease." (PMID 39215191, 2024). "The efficacy of PARPi therapy was initially demonstrated in high-grade serous ovarian cancer (referred to as OV hereafter) and breast cancer (BC), in which HRD was driven by germline pathogenic variants in either the BRCA1 or BRCA2 genes." (PMID 39055334, 2024). "BRCA1 and BRCA2 gene analyses are the most commonly performed tests used to determine the inheritance of breast cancer and are usually recommended for patients at high risk of cancer and their relatives, especially if there is a family history of cancer." (PMID 38753118, 2024). "Of the 294 oncogenic TFs, the androgen and estrogen receptors, the BRCA1 and BRCA2 genes, MYC and GATA3 stand out for their association with breast cancer subtypes." (PMID 37564937, 2023).
breast cancer (continued). "Using simulated case-control datasets, we show that the case-control LR method using age-specific breast cancer ORs from high-penetrance genes (e.g., BRCA1 and BRCA2) outperforms other OR analysis methods." (PMID 38725546, 2023). "BRCA1 and BRCA2 mutation carriers have a ~17–44% risk of ovarian cancer (OC) and ~69–72% risk of breast cancer (BC)." (PMID 36900415, 2023). "For example, in a previous study, the yield of BRCA1 and BRCA2 gene sequencing in ethnic Lebanese Arab women with high hereditary-risk breast cancer was much lower than predicted when compared to women of other ethnicities of the same age." (PMID 38201524, 2023). "ICD-9 codes starting with 17 seemed to repeat for the BRCA1 gene as this category denotes breast cancer." (PMID 37195695, 2023). "Germline mutations in BRCA1 and BRCA2, the most known breast cancer susceptibility genes, compromise DNA repair by homologous recombination and over 75% of tumours arising in women who inherit these mutations have a triple-negative phenotype." (PMID 37046584, 2023). "Breast cancer genes, BRCA1/2, are tumor suppressor genes located on chromosomes 17q21 and 13q12‐13, respectively, are mainly responsible for the maintenance of genome integrity through homologous DNA repair and control of cell cycle." (PMID 35908255, 2023). "It was recently shown that HspBP1 inhibits, in a BRCA1-dependent manner, the tumorigenesis of breast cancer in vitro and in vivo and promotes apoptosis." (PMID 37762371, 2023). "After reviewing the medical histories of (6052) women with BRCA1 or BRCA2 mutation, half of them developed breast cancer (especially TNBC) and faced a twofold increase risk of diabetes in the 15 years after breast cancer diagnosis." (PMID 37510134, 2023). "It is estimated that 70–80% of breast cancer patients with a BRCA1 or 2 mutation have a TNBC subtype, and that about 20% of TNBC have a BRCA1 or 2 mutation." (PMID 36831640, 2023). "As research on BRCA1 and breast cancer continues to evolve, it will become increasingly evident that modern materials such as Bisphenol A should be examined for their relationship with DNA stability, cancer incidence, and chemotherapy." (PMID 37762577, 2023). "In a third study, gene-based burden testing showed that there was an increase in carriers with BRCA1 and BRCA2 loss of function variants for breast cancer patients with an additional lung cancer." (PMID 37461096, 2023). "Development of hypomorphic BRCA1 isoforms has been described in patient-derived tumour xenografts (PDXs) from patients with germline BRCA1/2-mutant breast cancer resistant to PARPi." (PMID 37430137, 2023). "By performing immunohistochemistry, PAF-AH expression and β-catenin expression were examined in both BRCA1 WT and BRCA1 mutant breast cancer specimens." (PMID 36614323, 2023). "Among all breast cancer cases, approximately 5–10% are genetically inherited, with 3% occurring due to variations in the BRCA1/2 genes." (PMID 36834079, 2023). "Among patients and the established breast cancer susceptibility genes, PTVs in BRCA2 and ATM, followed by PALB2, and BRCA1, were the most prevalent." (PMID 37790698, 2023). "Approximately 11.2% of patients with TNBC carry germline variants in BRCA1 or BRCA2 genes, and they are usually diagnosed at a younger age and have a positive family history of breast cancer." (PMID 37656691, 2023). "Concretely speaking, the estimate of BRCA1 breast cancer incidence is 8.7‰ in the population of 20 to 29 years, while it rises to 36.1‰ when in the age group of 50 to 59 years." (PMID 37476378, 2023). "By the age of 80, women with BRCA1 and BRCA2 gene mutations have a cumulative risk of 72% and 69%, respectively, of developing breast cancer." (PMID 37835752, 2023).
breast cancer (continued). "The outcome of BRCA1/2 plasmid-loaded NPs delivery on cellular viability of three breast cancer cell lines such as MCF-7, MDA-MB-231 and 4T1 were evaluated by MTT assay." (PMID 36631481, 2023). "Using the classic cervical cancer cell line HeLa in culture, Crossley and coworkers achieved induction of cytoplasmic RNA–DNA accumulation by knocking down the RNA–DNA helicase (SETX) or the breast cancer gene BRCA1." (PMID 36902456, 2023). "HOXA9 is upregulated in leukemia but downregulated in breast cancer, where it acts as a tumor suppressor by regulating BRCA1 expression." (PMID 38203393, 2023). "In this study, we performed gene augmentation for BRCA1/2 tumor suppressors in order to retard tumor development in breast cancer mouse model." (PMID 36631481, 2023). "Intriguingly, endpoint analysis of the breast cancer cohort in this study determined that there was more pronounced activity in BRCA1/2 mutant patients, as determined by ORR rates of 47% compared to 11% and PFS of 8.3 months versus 2.1 months, respectively." (PMID 37035242, 2023). "In this prospective review of 15,104 women with breast cancer with 11-year median follow-up, CBC was seen in 5.3%, with a significant increase in women with BRCA1, BRCA2, and CHEK2 mutations (p < 0.05)." (PMID 37232811, 2023). "Likelihood ratios were calculated for a case-control dataset of BRCA1 and BRCA2 variants from the Breast Cancer Association Consortium (BCAC) and compared with logistic regression results." (PMID 38725546, 2023). "Other clinical responders whose tumors had biallelic LOF included two patients with CRPC (somatic ATM and CDK12 alterations) and one with germline BRCA1-altered breast cancer." (PMID 37277454, 2023). "Four Fanconi anemia (FA) genes (BRCA1, BRCA2, PALB2 and RAD51C) are defined as breast cancer (BC) susceptibility genes." (PMID 37566130, 2023). "The study found that BRCA1 and BRCA2 mutations were present in 2.5% and 3.7% of breast cancer patients, respectively, while PALB2 mutations were present in 0.6% of then." (PMID 38098088, 2023). "Clinical trial TBCRC 048 put forward that germline PALB2 or somatic BRCA1/2-mutant breast cancer responds well to PARPi." (PMID 37476378, 2023). "Our results suggest that BRCA1 breast cancers tend to be masses, posteriorly accentuating, and hypervascular." (PMID 36905492, 2023). "This study provides evidence for the first time that the co-occurrence of BRCA1/2 mutations and HER2-positive status is a poor prognostic factor in patients with early or locally advanced breast cancer." (PMID 37444415, 2023). "This highlights the growing importance of BRCA1/2 and PALB2 alterations in breast cancer susceptibility risk and the treatment of index patients." (PMID 38098088, 2023). "Hereditary pathogenic/likely pathogenic variants (P/LPVs) of BRCA1 and BRCA2 genes are the leading genetic causes of breast cancer (BC), ovarian cancer (OC), and other cancers (prostate, pancreas)." (PMID 36831416, 2023). "Patients with newly diagnosed early-stage breast cancer who carry a PV/LPV in BRCA1 or BRCA2 are often advised to undergo mastectomy, which can be skin-sparing or nipple-sparing." (PMID 37781190, 2023). "For example, BRCA1 and BRCA2 variants are found in only 1 in 400 women, but are associated with a full lifetime breast cancer risk of over 50%." (PMID 36749458, 2023). "Supporting our replication of h2 and h3 at chr11 is the report of a non-BRCA1/2 family from the Netherlands with six cases of breast cancer having a strong linkage peak at the 11q13 locus." (PMID 37541849, 2023).
breast cancer (continued). "In breast cancer cells, BRCA1 functions as a tumor suppressor gene that, when downregulated, leads to cellular proliferation and the accumulation of cellular ROS." (PMID 37107181, 2023). "In a Lebanese study, fewer than 6% of patients with early onset or familial breast cancer carried a known BRCA1 or BRCA2 PV, suggesting that alternative variants drive breast cancer incidence in this population." (PMID 37306523, 2023). "As BRCA1/2 mutant breast cancer patients already have existing defects in homologous repair, they are unable to effectively repair DNA damage, resulting in the generation of TSAs." (PMID 38263984, 2023). "FANCD2 is highly overexpressed in BRCA1/2 mutant breast cancers and contributes to DNA fork stability by inhibiting MRE11-mediated DNA replication fork degradation in BRCA1/2 mutant breast cancer cells." (PMID 37892162, 2023). "In the clinical genetics setting, BRCA1 penetrance to 80 years of 79.5% (95%CI 75.5–83.5%) for breast cancer and 65% (95%CI 75–84%) for ovarian cancer are reported, whereas population cohorts indicate lower risks." (PMID 36927983, 2023). "Among participants with a family history of breast cancer, PTVs in ATM, BRCA2, BRCA1, PALB2 and RAD50 were associated with an increased risk of breast cancer." (PMID 37790698, 2023). "Women with pathogenic germline variants in the BRCA1 or BRCA2 gene have an increased lifetime risk of breast cancer (BC) and ovarian cancer (OC), compared to the general female population, with cancer occurring about twenty years earlier than the sporadic forms." (PMID 37845719, 2023). "The concomitant lack of ER, PR, and HER2 defines Triple- Negative Breast Cancer (TNBC), a subtype that comprises 15-20% of all BC, highly prevalent in women younger than 40, Black, or with BRCA1 gene mutation, and represents the most challenging BC to be treated." (PMID 37265795, 2023). "In pathogenic BRCA2 and to lesser extent BRCA1 germline mutation carriers, the presence of RAD52 p.Ser346Ter was associated with reduced risk of breast cancer." (PMID 37578974, 2023). "Of note, BCLN1 and BRCA1 (a tumor suppressor gene) are physically close to each other, and deletion of BRCA1 in breast cancer patients can affect BCLN1." (PMID 37527766, 2023). "In breast cancer, the figure of over 2% for the germline contribution of BRCA1 and BRCA2 is a justified estimate, as is 5.6% for all known variants (applicable to the populations used in the study)." (PMID 36882784, 2023). "In breast cancer, although more than 75% of cases with BRCA1/2 alterations were LOH-high, >25% of BRCA1/2 wild-type (BRCA1/2wt) cases were LOH-high." (PMID 37173992, 2023). "Pathogenic variants in BRCA1 and BRCA2 confer a high life-time risk of breast cancer and increased risk of ovarian cancer." (PMID 37173335, 2023). "Here, we describe the case of a BRCA1/BRCA2 double heterozygous female proband diagnosed with breast cancer." (PMID 37895014, 2023). "Breast cancer is a heterogeneous disease characterized by different subtypes which are driven by aberrations in key genes such as BRCA1 and BRCA2, and hormone receptors." (PMID 37662839, 2023).